EFNA3 (ephrin A3)
Description:
Cell surface GPI-bound ligand for Eph receptors, a family of receptor tyrosine kinases which are crucial for migration, repulsion and adhesion during neuronal, vascular and epithelial development. Binds promiscuously Eph receptors residing on adjacent cells, leading to contact-dependent bidirectional signaling into neighboring cells. The signaling pathway downstream of the receptor is referred to as forward signaling while the signaling pathway downstream of the ephrin ligand is referred to as reverse signaling (By similarity).
Synonyms: EHK1-L; EFL2; EPLG3; LERK3
Tractability: Antibody: its Gene Ontology location is reachable by antibodies, with high confidence; UniProt places it where antibodies can reach, with medium confidence; UniProt predicts a signal peptide or a membrane-spanning region. PROTAC: its protein half-life has been measured.
Gene: Protein-coding gene on chromosome 1 (155,078,823 to 155,087,538, forward strand). Ensembl gene ENSG00000143590.
Subcellular location: Cell membrane
Pathways (Reactome):
Developmental Biology: EPH-Ephrin signaling; EPH-ephrin mediated repulsion of cells; EPHA-mediated growth cone collapse
Gene Ontology:
Molecular function: ephrin receptor binding; protein binding; transmembrane-ephrin receptor activity
Biological process: ephrin receptor signaling pathway; negative regulation of angiogenesis; positive regulation of amyloid precursor protein catabolic process; axon guidance; cell-cell signaling
Cellular component: plasma membrane; membrane
Genetic constraint (gnomAD): Loss-of-function variants: 15 observed, 22.36 expected, observed/expected ratio (o/e) 0.67, 90% interval 0.45 to 1.03. The upper end of that interval is the gene's LOEUF score, 1.03, which puts it in group 4 of 6, group 1 being the genes least tolerant of losing a copy. Missense variants: 298 observed, 311.75 expected, observed/expected ratio (o/e) 0.96, 90% interval 0.87 to 1.05. Synonymous variants: 153 observed, 133.9 expected, observed/expected ratio (o/e) 1.14, 90% interval 1 to 1.31.
Homologues: Orthologues: chimpanzee EFNA3 (100% identical), macaque EFNA3 (100% identical), pig EFNA3 (99% identical), dog EFNA3 (97% identical), guinea pig EFNA3 (95% identical), mouse Efna3 (93% identical), rat Efna3 (79% identical), rabbit EFNA3 (74% identical), zebrafish efna3b (59% identical), tropical clawed frog efna3 (42% identical), Caenorhabditis elegans efn-4 (20% identical), Caenorhabditis elegans vab-2 (19% identical), and 3 more. Paralogues in human: EFNA2 (37% identical), EFNA5 (37% identical), EFNA4 (36% identical), EFNA1 (34% identical), EFNB2 (24% identical), EFNB3 (23% identical), EFNB1 (22% identical).
Diseases named in the same sentence as EFNA3 in open-access papers:
EFNA3 is named in the same sentence as 65 diseases in open-access papers, as found by Europe PMC text mining. Sharing a sentence is not in itself a finding about the gene and the disease. The quoted sentences say what the papers report.
breast carcinoma (16 papers, 2013 to 2025). "Results displayed that HIF drives the expression of lncRNA-EFNA3 that causes Ephrin-A3 protein accumulation and contributes to metastatic spread of breast cancer." (PMID 31367258, 2019). "By overexpressing the various NC isoforms in breast cancer cell lines we were able to demonstrate that EFNA3 lncRNAs caused Ephrin A3 protein accumulation." (PMID 26682249, 2015). "Furthermore, we found a positive correlation between EFNA3 expression and risk of metastasis in breast cancer patients." (PMID 26682249, 2015). "Exosomes derived from tumor cells facilitate breast cancer angiogenesis by transferring miR-210 to endothelial cells, which suppresses the expression of Ephrin A3 and PTP1B while enhancing VEGF levels and promoting new vascular structure formation." (PMID 40404811, 2025). "Cellular interaction in breast cancer is based on EphA10 and EFNA3 expression, which binds to PD1 on T cells to inhibit immune activity and promote tumor tolerance." (PMID 35945523, 2022). "The first of them is the analysis of the role of long non-coding RNAs expressed from the EFNA3 (Ephrin-A3) locus after hypoxia on the metastatic phenotype of breast cancer cells." (PMID 35626715, 2022). "In response to hypoxia, lncRNA EFNA3 is induced in breast cancer (BC), leading to an accumulation of Ephrin-A3, both facilitating metastatic spread." (PMID 32992718, 2020). "Hypoxic breast cancer-derived exosomal miR-210 was proved to escalate into adjacent cells in the tumor microenvironment, promoting angiogenesis and metastasis in recipient cells by targeting Ephrin A3 and PTP1B, which are vascular remodeling-related genes." (PMID 35955480, 2022). "EFNA3 has been reported to promote the metastatic ability in breast cancer." (PMID 34603443, 2021). "In addition, a strong correlation between high lncRNA EFNA3 expression and shorter metastasis-free survival was found in breast cancer patients, undoubtedly enriching the prognostic value of lncRNAs in this prevalent cancer." (PMID 32014012, 2020). "Bioassay studies demonstrated that EFNA1, EFNA3, and EFNA4 expression were higher in breast cancer than in normal tissues, while EFNA5 showed an opposite trend." (PMID 35309935, 2022). "In the UALCAN database, the mRNA expression of EPHA1, EPHA10, EFNA1, EFNA3, and EFNA4 was significantly higher, whereas that of EPHA2, EPHA4, EPHA5, and EFNA5 was significantly lower in breast cancer tissues than in paracancerous tissues." (PMID 33977106, 2021). "In breast cancer, hypoxia-induced lncRNA EFNA3 leads to Ephrin-A3 protein accumulation and subsequent promoted matastasis." (PMID 26755660, 2016). "In breast cancer, ART increased EPHA8, EPHA10, EFNA2 and reduced EPHA3, EPHA7, and EFNA3." (PMID 38630320, 2024).
hepatocellular carcinoma (8 papers, 2013 to 2026). A malignant tumor that arises from hepatocytes. "For instance, EFNA3/EPHA2 axis can promote cancer stemness in hypoxic hepatocellular carcinoma by modulating metabolic plasticity, and EFNA3 is served as a prognostic biomarker for hepatocellular cancer." (PMID 37768204, 2023). "Tissue hypoxia has been shown to regulate EFNA3 that is a clinical prognostic and therapeutic predictor in lung adenocarcinoma and hepatocellular carcinoma." (PMID 38124114, 2023). "EFNA3 is highly expressed in GC, hepatocellular carcinoma, and other cancers." (PMID 35126464, 2021). "DCAF4L2 has been shown to promote the progression of liver cancer, while EFNA3 and SPP1 have been treated as prognostic targets for survival in hepatocellular carcinoma patients." (PMID 39628446, 2024). "To investigate the mechanism underlying the knockdown of miR-210 mediated tumor growth delay, we analyzed protein expression of HIF-1α gene and miR-210 targeted MNT, EFNA3 and AIFM3 genes in human hepatoma xenograft by Western blot." (PMID 23618526, 2013). "The Western blot results indicated that knockdown of miR-210 decreased HIF-1α protein and increased protein expression of MNT, EFNA3 and AIFM3 genes in human hepatoma xenograft." (PMID 23618526, 2013). "To investigate the mechanism underlying the knockdown of miR-210 mediated growth delay in SMMC-7721/Lv-anti-210 xenograft, we analyzed protein expression of HIF-1α, MNT, EFNA3 and AIFM3 genes in human hepatoma xenograft by Western blot." (PMID 23618526, 2013). "In hepatocellular carcinoma (HCC), EFNA3, promoted by HIF1-α under hypoxia conditions, affected the self-renew, proliferation and migration of HCC cells." (PMID 38630320, 2024).
gastric cancer (6 papers, 2021 to 2026). A primary or metastatic malignant neoplasm involving the stomach. "In our study, the expression of EFNA3 in gastric cancer was significantly higher than that of the adjacent tissues." (PMID 35309935, 2022). "To confirm the expression levels of SERPINE1 and EFNA3 in gastric cancer, we subsequently verified it in gastric cancer cell lines and patient tissues by qRT-PCR experiments." (PMID 34249015, 2021). "Among the identified DEGs, we found that 7 genes (IGFBP7, LOX, NRP1, PRSS3, DPP3, EFNA3, and CD73) were also differentially expressed in tumor tissues and associated with a poor or better prognosis in patients with gastric cancer." (PMID 34659527, 2021). "Correlation of EFNA3 mRNA expression and clinical prognosis in gastric cancer with different clinicopathological factors by Kaplan-Meier plotter Clinicopathological characteristics." (PMID 35126464, 2021). "Quantified real-time PCR was further applied to verified gene expressions of SERPINE1 and EFNA3 in gastric cancer patients and cell lines." (PMID 34249015, 2021). "Conversely, LINC01270 exhibits competitive endogenous (ce)RNA functions, as seen in its ability to sponge miRNA (miR)-326 to modulate the mRNA levels of LA-related protein 1 (LARP1) and Ephrin A3 (EFNA3), thus exacerbating lung cancer and gastric cancer progression, respectively." (PMID 39682774, 2024). "Mutual-exclusivity analysis between EFNA3 and multiple-immune checkpoints in gastric cancer." (PMID 35126464, 2021). "However, the relationship between EFNA3 and gastric cancer (GC) prognosis and tumor-infiltrating lymphocytes remains unclear." (PMID 35126464, 2021). "In terms of the influence on the survival of patients, the expression of EFNA3 and EFNA4 were related to overall survival (OS) and disease-free survival (DFS) for patients with gastric cancer." (PMID 35309935, 2022). "Our study found that TMB score and MSI was positively correlated with the expression of EFNA3 and EFNA4 in gastric cancer." (PMID 35309935, 2022). "The expression of EFNA1 (p = 1.62E-12), EFNA3 (p = 4.17E-07), and EFNA4 (p = 1.62E-12) were significantly increased in gastric cancer tissues." (PMID 35309935, 2022). "Compared with normal adjacent tissues, EFNA1, EFNA3, and EFNA4 were up-regulated in gastric cancer." (PMID 35309935, 2022). "Furthermore, the high expression of EFNA3 and EFNA4 indicates that it is beneficial for OS and DFS of gastric cancer, while the high expression of EFNA5 indicates a low survival rate." (PMID 35309935, 2022). "In gastric cancer, the expression of EFNA3 and EFNA4 showed a significant negative correlation with B cells." (PMID 35309935, 2022).
oral cancer (6 papers, 2020 to 2025). "A recent study revealed that EFNA3 has the potential to become a new target for oral cancer treatment through molecular biology techniques and xenotransplantation models." (PMID 35309935, 2022). "EFNA3 promotes the occurrence and development of oral tumors as well as the formation of blood vessels in oral cancer." (PMID 35126464, 2021). "In addition, it has been confirmed that EFNA3 could regulate the EMT process by the PI3K/AKT signaling pathway in oral cancer." (PMID 34645436, 2021). "EFNA3 is crucial in the progression of OSCC, indicating ephrinA3 as a promising target for oral cancer treatment." (PMID 40421081, 2025). "Although EFNA3 has not been extensively studied, available research in sheath tumor and oral cancers is gratifying." (PMID 35126464, 2021).
lung carcinoma (5 papers, 2013 to 2024). "We found that the EphA3 G518L lung cancer mutation strengthens the cis association of EphA3 with coexpressed ephrin-A3." (PMID 24348920, 2013). "We also found that an EphA3 mutation identified in lung cancer enhances cis interaction with ephrin-A3." (PMID 24348920, 2013). "We also found that a lung cancer mutation identified in the second fibronectin type III repeat of EphA3 enhances the cis association of the receptor with ephrin-A3." (PMID 24348920, 2013). "EFNA3 plays a pro-tumor role in lung cancer, while an anticancer effect in oral squamous cell carcinoma and peripheral nerve sheath tumor." (PMID 38630320, 2024). "Among these genes, six were already identified in the lung cancer related network of genes associated with RETC634Y signature (TMEM45B, CLDN1, TRIM29, SMUG1, SATB2, and EFNA3)." (PMID 38132167, 2023). "Recent data suggested that EFNA3 was selectively downregulated in tumor samples of lung cancer patients with COPD due to higher expression of miR-210." (PMID 34645436, 2021). "We indeed found that ephrin-A3 overexpressed in lung cancer cells can inhibit EphA2 and EphA3 activation by ephrins in trans while overexpression of ephrin-B2 can inhibit activation of EphA3 and EphB4." (PMID 24348920, 2013). "Thus, in lung cancer cells, coexpressed ephrin-A3 can inhibit EphA2 and EphA3 activation by ephrin ligands." (PMID 24348920, 2013). "However, we did not observe enrichment of EphA3 and ephrin-A3 in regions of cell-cell contact in A549 lung cancer cells coexpressing these proteins (not shown)." (PMID 24348920, 2013). "Thus, coexpressed ephrin-A3 in lung cancer cells inhibits ephrin binding to EphA3 in trans without reducing EphA3 expression or surface localization." (PMID 24348920, 2013).
myocardial infarction (5 papers, 2019 to 2025). Gross necrosis of the myocardium, as a result of interruption of the blood supply to the area, as in coronary thrombosis. "Local delivery of NMN preconditioned EVs promoted infarct healing through the improvement of angiogenesis by miR-210-3p via targeting the EFNA3 in a rodent animal model for myocardial infarction." (PMID 38649962, 2024). "Importantly, several studies indicate that miRNA-210 from extracellular vesicles could regulate the expression of EFNA3 to promote angiogenesis in ischemic hearts, oral squamous cell carcinoma, acute myocardial infarction, and ischemic disease models." (PMID 34645436, 2021).
lung adenocarcinoma (4 papers, 2021 to 2024). A carcinoma that arises from the lung and is characterized by the presence of malignant glandular epithelial cells. "In addition, GSEA showed that "cholesterol homeostasis," "glycolysis," and "oxidative phosphorylation" were enriched in the EFNA3-high expression group, suggesting that EFNA3 may be closely related to the metabolic ability of lung adenocarcinoma cells." (PMID 34645436, 2021). "In lung adenocarcinoma (LUAD), EFNA3 induces EMT by regulating ERK and p38MAPK pathway to affect the growth and metastasis of LUAD cells." (PMID 38630320, 2024). "To investigate whether EFNA3 can regulate cell proliferation ability in LUAD, we first detected the mRNA and protein expression levels of EFNA3 in human bronchial epithelial cells and lung adenocarcinoma cells." (PMID 34645436, 2021).
melanoma (3 papers, 2022 to 2025). A malignant, usually aggressive tumor composed of atypical, neoplastic melanocytes. "Evaluation of the predictive power of this novel signature in silico on an ICI-treated melanoma patient cohort extracted from GEO and EGA databases, revealed WFDC1, EFNA3, DDX10, and PTBP1 as marker genes." (PMID 35269844, 2022). "We further identified several melanoma-decreased genes uniquely up-regulated by ZDL, including growth factor receptor bound protein 7 (GRB7), neuronal guanine nucleotide exchange factor (NGEF), fatty acid amide hydrolase 2 (FAAH2), and ephrin A3 (EFNA3)." (PMID 40141086, 2025).
preeclampsia (3 papers, 2016 to 2025). Preeclampsia is a hypertensive disorder of pregnancy that is characterized by new-onset hypertension with proteinuria presenting after 20 weeks of gestation, and depending on mild or severe forms may initially present with severe headache, visual disturbances, and hyperreflexia. "As noncoding RNAs are an important part of evolutionary genetics and have been confirmed to play regulatory roles in preeclampsia, seven lncRNAs reported to be associated with hypoxia were selected, including UCA1, EFNA3, H19, MALAT1, HOTAIR, FALEC, and HAS2-AS1." (PMID 36160709, 2022). "Several target genes of miR-210 are known to be involved in preeclampsia, such as ACVR1B16, and studies have revealed that miR-210 could repress trophoblast cell invasion via modulating KCMF117, Ephrin-A3, Homeobox-A918, and THSD7A as shown in this study." (PMID 26796133, 2016).
angiosarcoma (2 papers, 2022 to 2024). A malignant tumor arising from the endothelial cells of the blood vessels. "For example, miR-210 has been shown to promote angiosarcoma cell proliferation by targeting ephrin A3 and E2F3, proteins involved in cell growth and division." (PMID 38826780, 2024).
glioma (2 papers, 2016 to 2024). A benign or malignant brain and spinal cord tumor that arises from glial cells (astrocytes, oligodendrocytes, ependymal cells). "Analogous findings have been reported for ephrins, with increased expression of ephrin-A3 and ephrin-A4 in ependymoma cell lines, of ephrin-B1 in medulloblastoma cell lines and rhabdomyosarcoma tumor cells, and of ephrin-B2 in gliomas and rhabdomyosarcoma tumor cells." (PMID 38612645, 2024).
metastatic disease (2 papers, 2023 to 2025). "Hypoxia also induces transcription of multiple lncRNAs from the EFNA3 locus in HIF-dependent manner, which post-transcriptionally stabilizes EFNA3 and aids in cancer cell extravasation into distant sites to develop metastatic tumors." (PMID 37583933, 2023). "Finally, we identified the EPHs (EPHA2, EPHA4, EPHA8, and EPHB4) and EFNs (EFNA1, EFNA3, EFNA4, and EFNB2) that are significantly overexpressed in the aggressive epithelioid histological subtype and revealed that the majority of EPHs/EFNs are overexpressed in metastatic disease." (PMID 41516312, 2025).
pancreatic cancer (2 papers, 2021 to 2023). "Its impact on downstream target genes like E2F3, EFNA3, GIT2, MNT, ZNF462, HOXA9, and EGR3 underscores its significance in shaping the aggressive phenotype of pancreatic cancer cells." (PMID 38132457, 2023).
Parkinson disease (2 papers, 2023 to 2025). A progressive degenerative disorder of the central nervous system characterized by loss of dopamine producing neurons in the substantia nigra and the presence of Lewy bodies in the substantia nigra and locus coeruleus. "Likewise, miR-92b-3p is an independent casual mediator from EFNA3 in Parkinson’s disease." (PMID 39643657, 2025).
Alzheimer disease (1 paper, 2018). A progressive, neurodegenerative disease characterized by loss of function and death of nerve cells in several areas of the brain leading to loss of cognitive function such as memory and language. "The most robustly increased transcript was Ephrin-A3 (Efna3) which belongs to the family of Ephrins that function in signaling between neurons and have been implicated in Alzheimer’s Disease, amyotrophic lateral sclerosis, and other neurological disorders." (PMID 30231063, 2018).
breast tumors (1 paper, 2024). "LRRC15 showed a strong expression in breast tumor tissues (100%), with +2 staining in 1% of the tissues and +3 staining in 99%, while EFNA3 exhibited strong positivity in 90% of the tissues, ranging from 0 (10%), +1 (17%), +2 (22%), to +3 (51%)." (PMID 38611080, 2024). "Furthermore, their in vivo findings revealed that breast tumors positive for EFNA3 exhibited an increased likelihood of metastasis to other organs." (PMID 38611080, 2024). "Based on these factors, LRRC15, EFNA3, TSPAN13, and CA12 were identified as transcripts with higher expression and prevalence levels in breast tumors, with low expressions in most of the control tissues." (PMID 38611080, 2024).
cerebral infarction (1 paper, 2021). An ischemic condition of the brain, producing a persistent focal neurological deficit in the area of distribution of the cerebral arteries. "At the end of the seven‐day treatment, the area of cerebral infarction, the expression changes of miRNA‐210 and ephrin A3 were determined." (PMID 34337881, 2021).
Cerebral ischemia (1 paper, 2021). Restriction of arterial blood supply to the brain associated with insufficient oxygenation to support the metabolic requirements of the tissue. "After cerebral ischemia, the expression of miRNA‐210 and its target gene, ephrin A3, will change accordingly." (PMID 34337881, 2021).